MSNP1 (moesin pseudogene 1)
Synonyms: formerly MSNL1
Gene: Processed pseudogene on chromosome 5 (25,909,503 to 25,911,234, forward strand). Ensembl gene ENSG00000251593.
Diseases named in the same sentence as MSNP1 in open-access papers:
MSNP1 is named in the same sentence as 2 diseases in open-access papers, as found by Europe PMC text mining. Sharing a sentence is not in itself a finding about the gene and the disease. The quoted sentences say what the papers report.
autism spectrum disorder (1 paper, 2016). A spectrum of developmental disorders that includes autism, and Asperger syndrome. "We previously identified the long noncoding RNA (lncRNA) MSNP1AS (moesin pseudogene 1, antisense) as a functional element revealed by genome wide significant association with autism spectrum disorder (ASD)." (PMID 27690106, 2016).
prostate carcinoma (1 paper, 2019). A carcinoma that arises from epithelial cells of the prostate gland. "MSN and MSNP1 were in the same PGG family and hsa-miR-96 potentially regulates MSN in the TCGA prostate cancer dataset." (PMID 31029062, 2019).